CCT7 (chaperonin containing TCP1 subunit 7)
Description:
Component of the chaperonin-containing T-complex (TRiC), a molecular chaperone complex that assists the folding of actin, tubulin and other proteins upon ATP hydrolysis. The TRiC complex mediates the folding of WRAP53/TCAB1, thereby regulating telomere maintenance.
Synonyms: CCTH; NIP7-1; CCTETA; TCP1ETA
Tractability: Small molecule: a structure with a bound ligand is known. PROTAC: UniProt records ubiquitination sites on it; ubiquitination databases record sites on it; its protein half-life has been measured.
Target class: Enzyme; Hydrolase
Gene: Protein-coding gene on chromosome 2 (73,233,420 to 73,253,021, forward strand). Ensembl gene ENSG00000135624.
Subcellular location: Cytoplasm
Subcellular location (Human Protein Atlas): Cytosol
Pathways (Reactome):
Metabolism of proteins: Association of TriC/CCT with target proteins during biosynthesis; Cooperation of PDCL (PhLP1) and TRiC/CCT in G-protein beta folding; Folding of actin by CCT/TriC; Formation of tubulin folding intermediates by CCT/TriC; Prefoldin mediated transfer of substrate to CCT/TriC
Signal Transduction: RHOBTB1 GTPase cycle; RHOBTB2 GTPase cycle
Gene Ontology:
Molecular function: protein binding; protein folding chaperone; ATP binding; ATP hydrolysis activity; ATP-dependent protein folding chaperone; identical protein binding
Biological process: positive regulation of protein localization to Cajal body; positive regulation of telomerase RNA localization to Cajal body; positive regulation of telomere maintenance via telomerase; protein folding; protein stabilization
Cellular component: chaperonin-containing T-complex; extracellular exosome; microtubule; cytoplasm; cytosol; cell body
Genetic constraint (gnomAD): Loss-of-function variants: 16 observed, 53.36 expected, observed/expected ratio (o/e) 0.3, 90% interval 0.2 to 0.46. The upper end of that interval is the gene's LOEUF score, 0.46, which puts it in group 2 of 6, group 1 being the genes least tolerant of losing a copy. Missense variants: 493 observed, 690.92 expected, observed/expected ratio (o/e) 0.71, 90% interval 0.66 to 0.77. Synonymous variants: 253 observed, 259.06 expected, observed/expected ratio (o/e) 0.98, 90% interval 0.88 to 1.08.
Homologues: Orthologues: chimpanzee CCT7 (100% identical), pig CCT7 (98% identical), guinea pig Cct7 (98% identical), macaque CCT7 (97% identical), rabbit CCT7 (97% identical), rat Cct7 (97% identical), mouse Cct7 (96% identical), tropical clawed frog cct7 (90% identical), zebrafish cct7 (89% identical), Drosophila melanogaster CCT7 (76% identical), Caenorhabditis elegans cct-7 (64% identical). Paralogues in human: TCP1 (35% identical), CCT2 (33% identical), CCT4 (32% identical), CCT3 (31% identical), CCT5 (28% identical), CCT6A (27% identical), CCT6B (26% identical), CCT8 (26% identical), PIKFYVE (25% identical), HSPD1 (21% identical), CCT8L2 (21% identical), MKKS (17% identical), and 1 more.
Diseases named in the same sentence as CCT7 in open-access papers:
CCT7 is named in the same sentence as 37 diseases in open-access papers, as found by Europe PMC text mining. Sharing a sentence is not in itself a finding about the gene and the disease. The quoted sentences say what the papers report.
hepatocellular carcinoma (4 papers, 2022 to 2025). A malignant tumor that arises from hepatocytes. "We investigated the diagnostic and prognostic value of CCT7 expression for hepatocellular carcinoma (HCC)." (PMID 35073517, 2022). "Elevated expression of CCT7 serves as a diagnostic biomarker for hepatocellular carcinoma." (PMID 41203126, 2025). "For example, there is a significant difference in the expression of TCP1/CCT2/CCT3/CCT4/CCT5/CCT6A/CCT7/CCT8 in hepatocellular carcinoma." (PMID 37058032, 2023). "CCT7 has prognostic value in endometrial cancer, hepatocellular carcinoma and breast cancer." (PMID 36404333, 2022). "CCT7 mRNA expression was significantly higher in HCC tissues than in normal liver tissues in the GSE25097, GSE63898 and TCGA liver hepatocellular carcinoma (LIHC) datasets." (PMID 35073517, 2022).
endometrial cancer (3 papers, 2021 to 2022). Primary or metastatic malignant neoplasm involving the endometrium (mucous membrane that lines the endometrial cavity). "Spliceosome signaling contributes significantly to the tumorigenesis and progression of several types of tumors, and previous research has suggested that CCT7 promotes the progression of endometrial cancer through this pathway." (PMID 35073517, 2022).
glioblastoma (3 papers, 2022 to 2025). The most malignant astrocytic tumor (WHO grade IV). "Increased expression of CCT2, CCT6A, and CCT7 in EVs from cavitron ultrasonic surgical aspirators (CUSA) samples in glioblastoma patients correlated with poor patient prognosis." (PMID 35749519, 2022). "Moreover, studies with glioblastomas demonstrated CCT6A, CCT1, CCT2, and CCT7 subunits increased in the tumor tissue and tumor-derived extracellular vesicles, particularly CCT6A." (PMID 40374617, 2025).
atherosclerosis (2 papers, 2015 to 2021). A disease characterized by the build-up of fatty material and calcium deposition in the arterial wall resulting in partial or complete occlusion of the arterial lumen. "Our data show very significant correlations between aortic expression of Cct7 and atherosclerosis (r = -0.39, p = 6.1x10-4) while hepatic expression was not correlated with lesion size (r = 0.003, p = 0.97)." (PMID 26694027, 2015).
carcinoma squamous cell (2 papers, 2019 to 2022). "According to the same authors, CCT7 has been linked to multiples cancer (neck cancer, adenocarcinoma, carcinoma squamous cell, neoplasms, malignant neoplasms and lymphoma) and health conditions (necrosis, staphylococcal scalded skin syndrome and Hodgkin disease)." (PMID 30704472, 2019). "A search against COSMIC identified a number of mutations found in tumors (i.e. adenocarcinoma, squamous cell carcinoma, malignant melanoma and clear cell renal cell carcinoma) localizing within fragments corresponding to SPATA22, ZBTB17, CCT7, MAP1S and PDIA3 proteins." (PMID 35205757, 2022).
glioma (2 papers, 2020 to 2025). A benign or malignant brain and spinal cord tumor that arises from glial cells (astrocytes, oligodendrocytes, ependymal cells). "Moreover, analyses of gene expression and DNA copy number showed that CCT2, CCT3, CCT5, CCT6A, and CCT7 are upregulated in GBM compared with normal brain tissue, while CCT2, CCT3, CCT5, CCT6A, and CCT8 display higher copy numbers than in low-grade gliomas." (PMID 41516249, 2025). "In particular, EVs obtained from CUSA (cavitron ultrasonic surgical aspirator) samples during GBM surgeries showed higher levels of all eight CCT subunits compared with those from low-grade gliomas, with CCT1, CCT2, CCT6A, and CCT7 being the most prominently upregulated." (PMID 41516249, 2025). "We previously reported significantly higher CCT2 and CCT7 levels in GBM neurosurgical aspirate-EVs compared to GII-III glioma, with analogous transcript expression levels and DNA copy numbers reported for CCT2 and CCT7 in GBM tissue compared to normal brain in TCGA datasets." (PMID 32635403, 2020).
virus infection (2 papers, 2024 to 2025). "To this end, we used the yeast two-hybrid system to identify the host cell protein CCT7 that interacts with CPV VP2, and further elucidate the role of CCT7 in virus infection." (PMID 38384266, 2024).
acute myelogenous leukemia (1 paper, 2022). "Instead, NPM1, which is involved in non-Hodgkin lymphoma and acute myelogenous leukemia, and CCTs (CCT4, CCT5, and CCT7) were up-regulated." (PMID 35464471, 2022).
asthma (1 paper, 2023). "Affinity capture studies indicate interactions between the protein products of RPS13, CCT7, and EPS15 and proteins involved in cell–cell and cell-ECM adhesion molecules relevant for asthma, such as VCAM-1, α4β1 integrin, and fibronectin." (PMID 36835202, 2023).
brain malformations (1 paper, 2025). "Recent reports provide evidence for presence of variants in several TRiC/CCT members including CCT1, CCT3, CCT5, CCT6A, CCT7 and CCT8, in brain malformations, seizures, and intellectual disability." (PMID 40779003, 2025).
Cirrhosis (1 paper, 2022). A chronic disorder of the liver in which liver tissue becomes scarred and is partially replaced by regenerative nodules and fibrotic tissue resulting in loss of liver function. "AFP mRNA levels in cirrhosis and HCC patients were similar in the two datasets, whereas CCT7 levels were significantly higher in HCC patients than in cirrhosis patients." (PMID 35073517, 2022).
colon cancer (1 paper, 2019). "CCT7 was also identified as a biomarker linked to late stage colorectal cancer in a protein interaction sub-networks analysis for early tumorigenesis comparing normal and late stage colon cancer tissues." (PMID 30704472, 2019).
myocardial infarction (1 paper, 2015). Gross necrosis of the myocardium, as a result of interruption of the blood supply to the area, as in coronary thrombosis. "For example, recent exome sequencing analysis of a highly affected family identified mutations in the gene CCT7 that impairs guanylyl cyclase signaling and increased risk of myocardial infarction and its role has been validated in mouse knockout studies." (PMID 26694027, 2015).
osteoporosis (1 paper, 2019). A condition of reduced bone mass, with decreased cortical thickness and a decrease in the number and size of the trabeculae of cancellous bone (but normal chemical composition), resulting in increased fracture incidence. "In addition, our analysis showed that lncRNA lnc-CCT7–3:1 was highly correlated with osteoporosis, its neighboring gene." (PMID 31164921, 2019).
Parkinson disease (1 paper, 2025). A progressive degenerative disorder of the central nervous system characterized by loss of dopamine producing neurons in the substantia nigra and the presence of Lewy bodies in the substantia nigra and locus coeruleus. "Here, we show that the apical domains of subunits CCT3 and CCT7 from humans are strong inhibitors of tau aggregation, which is associated with several neurological disorders such as Alzheimer's and Parkinson's diseases." (PMID 40400346, 2025).
cancer (9 papers, 2019 to 2025). A tumor composed of atypical neoplastic, often pleomorphic cells that invade other tissues. "Several CCT subunits, such as CCT2, CCT3, CCT4, CCT5, CCT6A, and CCT7, have been implicated in cancer progression." (PMID 40867231, 2025). "Another group of chaperone genes, such as CCT6A, CCT4, TCP1, CCT5, PTGES3 and CCT7, were previously implicated in cancer cell proliferation and predicts poor prognosis in HCC36,37." (PMID 33431814, 2021). "CCT7 expression is associated with cancer cell growth and maintenance, is downregulated during the DNA damage response in GBM and is associated with poor clinical outcome in GBM patients." (PMID 32635403, 2020). "CCT7 expression increased incrementally with increasing cancer stages and tumor grades, and was greater in metastatic than in non-metastatic tumor samples." (PMID 35073517, 2022). "In addition, CCT7 mRNA levels in HCC samples increased incrementally with increasing cancer stages and tumor grades." (PMID 35073517, 2022). "Furthermore, there were differences for CCT4 (P = 0.0123) and CCT7 (P = 0.09886) in the mRNA expression levels and patients’ N stage, a staging system developed by the American Joint Committee on Cancer to classify patients by the involvement of regional lymph nodes." (PMID 33313411, 2020). "Some of the genes were reported as cancer-related genes, such as CCT2, CCT3, CCT4, CCT6A, CCT7, CCT8." (PMID 33897772, 2021). "Based on the Oncomine database, we found that mRNA expressions of TCP1, CCT2, CCT6A, CCT7, STIP1 and HSP90AB1 were significantly upregulated in cancerous samples compared with normal samples in various types of cancer, including BC." (PMID 32194784, 2020).
tumor (9 papers, 2019 to 2025). "A univariate Cox regression analysis indicated that greater vascular invasion (P = 0.003), TNM staging (P < 0.001), tumor grading (P < 0.001) and CCT7 mRNA expression (P < 0.001) were risk factors for poorer OS in HCC patients." (PMID 35073517, 2022). "The expression levels of CCT4 and CCT7 demonstrated to be significantly associated with the tumor stage of HNSC, and only CCT4 was related to patients’ N stage." (PMID 33313411, 2020). "A univariate Cox regression analysis revealed that greater tumor sizes (P = 0.038), TNM staging (P = 0.006), tumor differentiation (P = 0.012), vascular invasion (P = 0.040) and CCT7 protein expression (P = 0.048) were risk factors for poorer OS in HCC patients." (PMID 35073517, 2022). "Higher CCT7 protein expression was associated with higher TNM staging (P = 0.043), serum AFP expression (P < 0.001), tumor differentiation (P = 0.010), vascular invasion (P = 0.029) and recurrence (P = 0.005) in HCC patients." (PMID 35073517, 2022). "On the other hand, except metabolism, the derived genes are also associated with distinct modes of tumor physiology in CRC, such as detoxification (GSTP1), metastasis (KIT), immunomodulation & stem cell renewal (CD44) and ER stress (CCT7)." (PMID 30809322, 2019). "According to GSE32863 sequencing data, increased expression of CCT3, CCT4, CCT5, CCT6A, CCT7, and CCT8 was observed in LUAD tumor tissues compared with paired normal tissues." (PMID 39259093, 2024). "In conclusion, GP5, CCT7, UQCRC1, PGD, GAPDH and LDHA have been found to play a role in tumor development, prognosis and even diagnosis in previous studies." (PMID 36404333, 2022). "In the TNMplot database, CCT7 mRNA expression was higher in metastatic samples than in non-metastatic tumor samples or normal samples." (PMID 35073517, 2022). "In summary, our results indicated that subunits of TRiC displayed varying degrees of abnormal expressions, and CCT2, CCT3, CCT5, CCT6A, CCT7, and CCT8 were significantly upregulated in BCa patients and their upregulation was positively correlated with BCa tumor stage." (PMID 33815471, 2021).
infection (1 paper, 2024). The state of being infected such as from the introduction of a foreign agent such as serum, vaccine, antigenic substance or organism. "To further determine the interaction of VP2 with CCT7, we infected F81 cells with CPV (MOI = 0.1) and collected the cells at 24 h post-infection." (PMID 38384266, 2024).
CCT7 also shares sentences with these, for which no sentence is quoted: breast carcinoma (3 papers); adenocarcinoma (2); airway hyperresponsiveness (1); clear cell renal cell carcinoma (1); colorectal cancer (1); familial cancer (1); Hodgkin disease (1); Intellectual disability (1); keratoconus (1); lung carcinoma (1); lymph node metastasis (1); lymphoma (1); malignant melanoma (1); neck cancer (1); neurological disorders (1); non-Hodgkin lymphoma (1); osteosarcoma (1); staphylococcal scalded skin syndrome (1); urothelial carcinoma (1).